TBP (TATA-box binding protein)
Diseases named in the same sentence as TBP in open-access papers (continued):
Sharing a sentence is not in itself a finding about the gene and the disease.
anemia (1 paper, 2023). A reduction in the number of red blood cells, the amount of hemoglobin, and/or the volume of packed red blood cells. "TBP, MAPK1, and RPP30 are the most stable genes that are uninterrupted by anemia, OIR and EPO administration." (PMID 37098032, 2023).
atherosclerosis (1 paper, 2020). A disease characterized by the build-up of fatty material and calcium deposition in the arterial wall resulting in partial or complete occlusion of the arterial lumen. "Our recent study on this topic is about 34 candidate SNP markers of atherosclerosis that are located around the clinical SNP markers in TBP-sites of 17 human gene promoters." (PMID 32033288, 2020).
autoimmune disease (1 paper, 2016). A disorder resulting from loss of function or tissue destruction of an organ or multiple organs, arising from humoral or cellular immune responses of the individual to their own tissue constituents. "Known and nearby candidate SNP markers (of autoimmune diseases) that can change affinity of TBP for a human gene promoter." (PMID 27092142, 2016).
cardiomyopathy (1 paper, 2014). A disease of the heart muscle or myocardium proper. "Importantly, the TATA box of the wild-type TPI genepromoter requires lower TBP concentrations compared to the TATA box containingthe -24T → G SNP, which is associated with neurological and musculardisorders, cardiomyopathy, and other diseases." (PMID 25093109, 2014).
cerebellar degeneration (1 paper, 2014). Degeneration of the cerebellum. "Because complete elimination of HSPA5 in Purkinje cells leads to reduced cytosolic ubiquitination and accelerated cerebellar degeneration in a mouse model, HMGB1 could be a target of mutant TBP in SCA17, as well as NFYA." (PMID 25549101, 2014).
clear cell renal cell carcinoma (1 paper, 2007). "Our study demonstrated the suitability of the two housekeeping genes PPIA and TBP as endogenous reference genes when comparing malignant tissue samples with adjacent normal tissue samples from clear cell renal cell carcinoma." (PMID 17559644, 2007).
Cluster headache (1 paper, 2019). A type of headache characterized by repeated attacks of unilateral pain lasting 15 to 180 minutes and associated with local autonomic signs. "Also, we determined that TBP, IPO8 and PDHB were suitable reference genes in cluster headache fibroblasts." (PMID 31366133, 2019).
co-infection (1 paper, 2021). "Based on PCR and sequencing results, we found a high TBP prevalence, including a high level of co-infection with other TBP species from the two groups Theileria/Babesia and Anaplasma/Ehrlichia, while none of the cattle samples tested positive for Rickettsia spp." (PMID 34959550, 2021).
Cognitive impairment (1 paper, 2024). Abnormal cognition is characterized by deficits in thinking, reasoning, or remembering. "Regarding the SCATBP/STUB1, we found that apart from more common cognitive impairment and movement disorders, the prevalence of other symptoms did not significantly differ from those observed in the SCA48, which may due to the TBP duplication." (PMID 39707479, 2024).
colorectal adenoma (1 paper, 2017). An adenoma that arises from the colon or rectum. "Given that TBP expression is statistically increased in at least one cohort of colorectal adenomas relative to normal colon, dysregulation of TBP expression may be an early event in tumor development." (PMID 28415573, 2017).
colorectal tumors (1 paper, 2017). "In both matched and unmatched samples from the TCGA database and additional three datasets from published sources, relative TBP expression was significantly higher in colorectal tumors compared to normal tissue." (PMID 28415573, 2017). "Oncomine was further used to identify datasets that measured changes in TBP expression between normal tissues and colorectal tumors." (PMID 28415573, 2017). "Given our findings that TBP regulates VEGF expression, we compared relative TBP and VEGFA expression in normal tissue and colorectal tumors in the five publicly available datasets as they were all shown to have increased TBP in tumors compared to the normal tissues." (PMID 28415573, 2017).
COVID-19 (1 paper, 2022). A disease caused by infection with severe acute respiratory syndrome coronavirus 2. "Our study identifies CypA and then TBP as the two most suitable reference genes for COVID-19 and CAM." (PMID 36377893, 2022).
embryonic carcinoma (1 paper, 2015). "It has also been reported that, unprocessed TFIIAαβ in P19 embryonic carcinoma cells forms a complex with TBP and TFIIAγ, which is referred to as TAC (TBP-TFIIA-containing) complex." (PMID 26038314, 2015).
endometriosis (1 paper, 2014). The growth of functional endometrial tissue in anatomic sites outside the uterine body. "It was postulated that endometriosis related oxidative stress resulted in a decrease in TBP-2 rather than an increase in TRX and hence the change in the TRX/TBP ratio." (PMID 24900998, 2014).
head and neck cancer (1 paper, 2017). A primary or metastatic malignant neoplasm affecting the head and neck. "Data analysis and ranking of the top 5 HKGs using geNorm and Normfinder identified UBC, TBP, IPO8, TFRC, GAPDH in head and neck cancer; TBP, IPO8, GUSB, UBC in lung and TBP, IPO8, TFRC, GUSB, HMBS in pancreas to be stable." (PMID 28262749, 2017). "Unlike head and neck cancer cell lines, TBP was stably expressed in A549 and NCI-H226 across all IR dose treatment groups while PP1A, GAPDH and B2M expression was exclusively expressed at 2, 4 and 6 Gy respectively." (PMID 28262749, 2017).
liver fibrosis (1 paper, 2025). "We found that high fat upregulated TBP and β-TrCP, which induced membrane TIM3 polyubiquitination and activation, thereby promoting liver fibrosis." (PMID 40251185, 2025). "Now, we found that TBP is abnormally activated in macrophages, and directly transcriptionally activates TIM3 at the liver fibrosis stage of NASH." (PMID 40251185, 2025).
lung adenocarcinoma (1 paper, 2023). A carcinoma that arises from the lung and is characterized by the presence of malignant glandular epithelial cells. "The copy numbers of both the target (CYP2C8, CYP3A4) and the reference genes (ALB, B2M, BCKDHA, F5, CD36, MPO, TBP, RPPH1) established in primary lung adenocarcinoma by the qPCR-based method were congruent with those determined by next-generation sequencing (for 10 genes, slope = 0.9498, r2 = 0.72)." (PMID 37686184, 2023).
lung carcinoma (1 paper, 2019). "The genes tested were TBP as a housekeeping gene, EGFR, ERCC1 and RRM1 as genes with potential predictive roles for lung cancer therapy, and HIF1 as a gene regulated by hypoxia, at least partially on RNA level." (PMID 30947297, 2019).
lymph node metastases (1 paper, 2008). "In a separate study conducted with a small set of tissues (n=14), we observed that B2M maintained its high prognostic accuracy for lymph node metastases (AUC=0.79) when more classical reference control genes TBP or UBP were substituted for Spint2 (not shown)." (PMID 18506145, 2008).
meningioma (1 paper, 2011). A generally slow growing tumor attached to the dura mater. "Established housekeeping genes in meningioma RT-qPCR experiments are genes such as glyceraldehyde-3-phosphate dehydrogenase (GAPDH) and β-Actin (ACTB) as well as ribosomal RNA (18S rRNA) and TATA binding box protein (TBP)." (PMID 21806841, 2011).
mucormycosis (1 paper, 2022). "Application of statistical algorithms identifies CypA and TBP as the most appropriate reference genes for SARS-CoV-2 infection and associated mucormycosis." (PMID 36377893, 2022).
multinodular goiter (1 paper, 2019). Nodular goiter characterized by more than one discrete tissue mass. "The expression characteristics of 12 candidate reference genes (GAPDH, ACTB, HPRT1, TBP, B2M, PPIA, 18SrRNA, HMBS, GUSB, PGK1, RPLP0, and PGM1) were assessed by qRT-PCR in 45 thyroid tissue samples (15 papillary thyroid carcinoma, 15 paired normal tissues and 15 multinodular goiters)." (PMID 31645594, 2019).
nasal polyps (1 paper, 2018). "In intact RNA, they found that the genes for hydroxymethyl-bilane synthase (HMBS) and succinate dehydrogenase complex, subunit A (SDHA) in CRS, and ACTB and TBP in nasal polyps were the most stable among nine candidate reference genes analysed using geNorm." (PMID 29371606, 2018).
neurofibroma (1 paper, 2021). An intraneural or extraneural neoplasm arising from nerve tissues and neural sheaths. "In a previous study, TBP was also proven to be a stable reference gene in Schwann cells derived from neurofibromas." (PMID 33630851, 2021).
non-small cell lung carcinoma (1 paper, 2017). A group of at least three distinct histological types of lung cancer, including non-small cell squamous cell carcinoma, adenocarcinoma, and large cell carcinoma. "Paired and single cell line analyses under these experimental conditions identified TATA-Box Binding Protein (TBP) and Importin 8 (IPO8) to be stable in non-small cell lung cancer." (PMID 28262749, 2017).
parasitic disease (1 paper, 2025). "Overall, this work identified a potential inhibitor targeting the general transcription factor TBP of T. cruzi, potentially paving the way for developing targeted therapies for this parasitic disease." (PMID 40573241, 2025).
periodontitis (1 paper, 2017). An acute or chronic inflammatory process that affects the tissues that surround and support the teeth. "PPIB and TBP are most stably expressed in hPDL fibroblasts stimulated with Agac toxins and should therefore be used for in vitro experiments on periodontitis." (PMID 29116140, 2017).
rheumatoid arthritis (1 paper, 2021). A chronic, systemic autoimmune disorder characterized by inflammation in the synovial membranes and articular surfaces. "Candidate SNP markers of rheumatoid arthritis (RA) that are located near TBP-sites of human gene promoters as predicted in this work, in comparison with genome-wide patterns." (PMID 34239535, 2021).
serous ovarian tumor (1 paper, 2021). "During serous ovarian tumor formation, activated AHR in the cytoplasm could cooperate with SRC, enter cell nuclei, bind to AHR nuclear translocator (ARNT) together with TATA-Box Binding Protein (TBP), and act on DNA to initiate AHR-responsive genes to cause tumor or cancer initiation." (PMID 34440070, 2021).
tongue cancer (1 paper, 2018). A malignant neoplasm affecting the tongue. "HDAC2, TBP, and EP300 scored ≥10 on Maximal Clique Centrality (MCC) in STEM profile 11 and were overexpressed in human tongue cancer samples." (PMID 30135512, 2018).
Tremor (1 paper, 2024). An unintentional, oscillating to-and-fro muscle movement about a joint axis. "In particular, numerous monogenic neurodegenerative, neuropathic and metabolic diseases manifest with tremor often accompanied by signs of other movement disorders, especially of a dystonic (e.g. ANO3, SGCE), ataxic (e.g. PPPP2R2B, ATX3, TBP) or parkinsonian (e.g. LRRK2, FMR1, ATX3) type." (PMID 39346806, 2024).
tuberculosis (1 paper, 2024). A chronic, recurrent infection caused by the bacterium Mycobacterium tuberculosis. "The TBDM patients were characterized by an elevated Mycobacterium tuberculosis-specific QFT-P IFN-γ response after TB treatment compared to the TBP group (p<0.001 and p<0.05, respectively, after TB1 and TB2 antigens stimulation)." (PMID 39896818, 2024).
cancer (45 papers, 2009 to 2025). A tumor composed of atypical neoplastic, often pleomorphic cells that invade other tissues. "TBP plays a significant role in regulating gene expression and has been implicated in various cellular processes, including those involved in cancer progression." (PMID 39434688, 2024). "The second case includes various examples, particularly in cancer research, in which DNA-reactive alkylating compounds interfere with the accurate recruitment of TBP at the promoter site of target genes." (PMID 40573241, 2025). "Conventional reference genes such as GAPDH, TBP, or miR-16-5p, frequently chosen based on historical usage rather than empirical evidence, show considerable variability in contexts like cancer, metabolic disorders, and biofluids prone to hemolysis." (PMID 41216219, 2025). "The discovery of MROH8’s involvement in TBP regulation adds a new dimension to the understanding of TBP function in cancer." (PMID 39434688, 2024). "Some research indicates that TBP can bind to DNA damaged by cisplatin or UV radiation, which are used in the treatment of cancer." (PMID 36903861, 2023). "TFIIIB, an RNA polymerase III specific transcription factor has been found to be deregulated in human cancers with much of the research focused on the TBP, BRF1, and BRF2 subunits." (PMID 36305848, 2023). "Most of the down-regulated hub proteins (ESR1, MCL1, LCK, TBP, and PCNA) play roles in the proliferation or survival of cancer cells, and CHEK1 is associated with the cell cycle checkpoint in cancer cells." (PMID 35563525, 2022). "Since the oncogenic signaling pathways that regulate TBP expression are deregulated in many human tumor types it is likely that enhanced TBP expression occurs in other human cancers as well." (PMID 28415573, 2017). "MYC is involved in cell proliferation and its persistent expression is common to many cancers, while TBP is related to RNA polymerase II, an essential element of DNA transcription initiation." (PMID 24932011, 2014). "Pathways that are enriched in cancers of diverse origins ranked highly in both Basal-like and murine TBP tumors." (PMID 23173005, 2012). "The other case comprises multiple examples, especially in the field of cancer, where alkylating agents that bind to DNA hinder the proper assembly of the TBP on the gene promoter region, interacting with the concave region of the TBP’s characteristic saddle-shaped structure." (PMID 38892424, 2024). "However, TBP’s role in m6A processes remains underexplored, especially regarding its interaction with other regulatory proteins in different cancer types." (PMID 39434688, 2024). "RNU2-2P is a pseudogene that is involved in cancer and is inhibited by TBP, TAF5 and GTF2B." (PMID 38674117, 2024). "Our findings support the idea that enhanced TBP expression might be clinically important in human cancers." (PMID 28415573, 2017). "Additionally, recent findings have linked TBP to m6A modifications, showing that TBP can influence m6A methylation processes by promoting the expression of key m6A writers such as METTL3, which enhances RNA stability and translation in cancer cells." (PMID 39434688, 2024). "Therefore, understanding TBP’s broader role in m6A-related regulation may provide new insights into its contribution to cancer progression." (PMID 39434688, 2024). "TATA-box-binding protein (TBP)-associated factor 1 (TAF1) is a key component of RNA polymerase II and is known to play a critical role in the regulation of cell growth and the cell cycle, whereas its role in cancer development is largely unknown." (PMID 38045002, 2023). "Taken together, our findings indicate that ECGC efficiently disrupts c-MYC:TBP and c-MYC:TRRAP complex formation in cancer cells." (PMID 38424045, 2024). "An example of this has been reported for the experimental cancer treatment drug, CX-5461, which inhibits the interaction between RNApol1 and the SL1/TBP complex, preventing pre-initiation complex formation." (PMID 38892424, 2024).
cancer (continued). "TBP expression also correlates with the expression of MYC, RAS and checkpoint kinases in a number of cancers." (PMID 27725641, 2016). "Our anti-TAF2 antibody was able to immunoprecipitate endogenous TAF2, as well as core subunits of the TFIID complex, including TBP, TAF4, TAF5, TAF6, and TAF7, in nuclear extracts from colorectal HCT116, embryonic kidney HEK-293, and ovarian A2780 cancer lines." (PMID 38773077, 2024). "CNV-TFs TBP and NFYB targeted HSPA2, HSPA8 and HSPA1A respectively, three members of heat shock protein 70 which could inhibit apoptosis in cancer cells through simultaneous and independent mechanisms." (PMID 24897108, 2014). "Recently, both HPRT1 and TBP were indicated as suitable reference genes for differential expression studies using qRT-PCR in different type of cancers, moreover HPRT1 was recommended as a universal single reference gene for expression analysis in cancer." (PMID 19257903, 2009). "A small number of hypoxia-associated genes (APLN, HIF1A, and BNIP3), cancer stem cell (CSC) markers (CD24 and CD44), hormonal regulation (HR) genes (ESR1, PGR, and TFF1), other selected genes (PPARGC1A, ILK), and HKGs (RPL32, GUSB, TBP, OAZ1 and NONO) were also included in the panel." (PMID 34206049, 2021). "We found that MHC-I scores were higher in cancer cells without expression of PIP5K1A, NCKAP1, CYFIP1, DIS3, TBP, and EXCO1." (PMID 39408874, 2024). "In contrast, for the three reference genes (B2M, TBP and UBC), neither or only one of the two guide RNAs (gRNAs) targeting each gene showed increased repression fold changes in cancer." (PMID 39478119, 2024). "We also found that six genes (TBP, EP400, DSPP, MUC21, MLLT3, and MUC2) were under negative selection in more than five cancer types." (PMID 28938601, 2017). "Interestingly, we observed that GAPDH, GUSB, IPO8, RPL13, RPL32, and UBC genes, as well as RPLP0 + TBP, RPL13 + RPL32, RPL13 + RPLP0, and ACTB + TBP RG pairs, were the only assays whose expression did not depend (P > 0.05) on cancer progression." (PMID 25225161, 2014).